CTSK (cathepsin K)
Diseases named in the same sentence as CTSK in open-access papers (continued):
Sharing a sentence is not in itself a finding about the gene and the disease.
osteoporosis (continued). "For this reason, there is growth pharmaceutical interest focuse on developing the cathepsin K inhibitors to control the bone resorption, although cathepsin K inhibitors have failed in osteoporosis clinical trials." (PMID 33751248, 2021). "The history of cathepsin drug discovery has in fact witnessed the development of pharmacological cathepsin inhibitors, especially for cathepsin K during inflammatory conditions, as for osteoporosis or arthritis." (PMID 34421929, 2021). "Specific inhibition of cathepsin K has therefore been a new drug target for diseases that have elevated bone resorption such as osteoporosis." (PMID 32117071, 2020). "A study on the genetics and pathophysiology of pycnodysostosis revealed the role of cathepsin K in osteoclast activity that led to the development of cathepsin K inhibitors to treat osteoporosis by inhibiting osteoclastic bone resorption." (PMID 32733380, 2020). "The authors show that silencing cathepsin K in osteoclasts by delivering an artificial miRNA via bone-homing AAV9 can counteract bone loss in mouse models of postmenopausal and senile osteoporosis." (PMID 32405514, 2020). "One of such exosite inhibitors of cathepsin K was successfully demonstrated in a mouse model of osteoporosis." (PMID 32668602, 2020). "While inhibitors of cathepsin B and S are currently being evaluated in clinical trials, recent failure of Odanacatib, a cathepsin K inhibitor for osteoporosis, in late stage clinical trial has made pharmaceutical industries wary of targeting cathepsins." (PMID 32041276, 2020). "Monoclonal antibodies directed to inhibiting sclerostin and cathepsin K inhibitors have been generated for the treatment of osteoporosis." (PMID 31281368, 2019). "The key role of cathepsin K in bone resorption makes the protease an attractive therapeutic target in disorders where bone resorption is excessive, e.g. osteoporosis and in joint diseases involving bone, such as osteoarthritis (OA)." (PMID 29743078, 2018). "The effectiveness of pharmacological cathepsin K inhibition as a treatment for bone diseases such as osteoporosis and osteoarthritis has been demonstrated in the literature." (PMID 30406161, 2018). "Selective cathepsin K inhibitors increase bone mineral density in ovariectomized monkeys and clinically in post-menopausal women with osteoporosis." (PMID 29523155, 2018). "Odanacatib (ODN), an inhibitor of cathepsin K, is currently being developed as a treatment for osteoporosis." (PMID 29692856, 2018). "Cathepsin K is an attractive therapeutic target for diseases in which bone resorption is excessive such as osteoporosis and osteoarthritis (OA)." (PMID 29743078, 2018). "In clinical studies, the cathepsin K inhibitor ONO-5334 reduced urinary CTX-II by 50% after treatment of postmenopausal women with osteoporosis for 12 months." (PMID 29743078, 2018). "Development of newer agents such as cathepsin k inhibitor and strontium ranelate not only have increased the available options for treating osteoporosis, but also have opened doors of opportunity to improvements in the effective treatment." (PMID 28173850, 2017). "Inhibitors of cathepsin K have received a lot of attention and many of them reached clinical trials, particularly for the treatment of osteoporosis." (PMID 28904354, 2017). "ONO-5334 is a cathepsin K inhibitor that induced bone mineral density (BMD) gain in a phase II study in postmenopausal osteoporosis patients." (PMID 28629344, 2017). "Cathepsin K has been reported to be a cysteine protease involved in the bone remodeling and resorption related to osteoporosis." (PMID 29262817, 2017). "These cytokines also stimulate the production of RANKL/MCSF, which activates osteoclasts producing cathepsin K (Cat K) and matrix metalloproteases (MMPs) resulting in bone damage such as osteoporosis." (PMID 28005963, 2016). "are generated by cathepsin K during the bone resorption process and are used as biochemical markers of osteoporosis." (PMID 26949397, 2016).
osteoporosis (continued). "Inhibition of cathepsin K represents a potentially effective therapeutic approach for treating diseases characterized by excessive bone resorption, such as osteoporosis." (PMID 25260821, 2015). "The best studied example of this mode of regulation is cathepsin K, the principal peptidase in bone turnover and a promising target for the treatment of osteoporosis." (PMID 25184245, 2014). "Here we investigate the mechanisms of allosteric regulation of cathepsin K as a representative of cysteine cathepsins and a promising drug target for the treatment of osteoporosis." (PMID 25184245, 2014). "Due to its potential role in osteoporosis, cathepsin K is currently one of the cysteine proteinases most intensively investigated by the pharmaceutical industry." (PMID 23951042, 2013). "More recently, ovariectomized cynomolgus monkey, a known postmenopausal osteoporosis model, was subject to a long-term treatment with a cathepsin K inhibitor and showed an unexpected stimulatory effect on periosteal bone formation." (PMID 22666151, 2012). "Indeed, cathepsin K deficiency has been linked to bone disorders such as pycnodysostosis and osteopetrosis, while the excessive activity of this enzyme may lead to osteoporosis, making it a likely target for rational drug design." (PMID 21794126, 2011). "Recently, Cathepsin K was regarded as a potential target for therapeutic intervention of osteoporosis." (PMID 21695131, 2011). "Cathepsin K, a cysteine protease predominantly expressed in osteoclasts, is a major drug target for the treatment of osteoporosis." (PMID 21627832, 2011). "This is of highest importance in light of recent advances in the development of targeted cathepsin K inhibitors, aimed at treating osteoporosis." (PMID 21794126, 2011). "Cathepsin K is a key enzyme in the process of bone resorption and its inhibition is a new therapeutic target for the treatment of osteoporosis." (PMID 20948576, 2010). "Cathepsin K therefore plays a role in bone remodelling and resorption in diseases such as osteoporosis, osteolytic bone metastasis and rheumatoid arthritis (RA)." (PMID 15642144, 2005). "Cathepsin K therefore plays a role in bone remodelling and resorption in diseases such as osteoporosis, osteolytic bone metastasis and rheumatoid arthritis." (PMID 15642144, 2005). "It regulates the synthesis and release of cathepsin K and may be a potential target for the treatment of bone turnover or osteoporosis." (PMID 40104299, 2025). "Thus, palm tocotrienol’s ability to suppress osteopontin, αvβ3 integrin, and cathepsin K highlights its potential as an osteoporosis therapy." (PMID 41155499, 2025). "Cathepsin K inhibitors are known treatments for osteoporosis by blocking bone resorption." (PMID 41155499, 2025). "Renewed efforts in this direction could unlock new opportunities to develop these compounds as effective and sustainable alternatives to synthetic inhibitors for Cathepsin K-related conditions, such as osteoporosis and cancer." (PMID 39795149, 2024). "This review focuses on osteoporosis, a major skeletal disorder driven by excessive bone resorption, and examines the physiological effects, clinical outcomes, and reasons for discontinuation of Cathepsin K inhibitors developed to date." (PMID 39795149, 2024). "Salvia miltiorrhiza Bunge, which targets different pathways in the bone remodeling cycle, including activation of osteoblasts, inhibition of osteoclast generation, and degradation of collagen by cathepsin K, has been proven in clinical practice to have good anti-osteoporosis potential." (PMID 38707332, 2024). "For markers of bone resorption we focused on CTX-I, which is formed by the degradation of the C-terminus of type I collagen by cathepsin K, which has now been recommended by the International Osteoporosis Foundation as a reference index reflecting bone resorption." (PMID 37277810, 2023).
osteoporosis (continued). "Because UBAP2 mRNA expression was correlated with the osteoclastogenesis-related genes ACP5 and CTSK in the bone marrow samples of patients with osteoporosis, we further investigated to identify the UBAP2 associated molecule(s) involved in osteoclast differentiation." (PMID 37339951, 2023). "This mode of regulation received more attention with the discovery that C4-S from cartilage prominently increased the collagenolytic activity of cathepsin K. Due to its central role in bone turnover, cathepsin K is considered one of the most promising targets for the treatment of osteoporosis." (PMID 36979788, 2023). "Moreover, cathepsin K is crucial for the treatment of osteoporosis and is also involved in cell protein turnover, collagen degradation, extracellular matrix remodeling, maintenance of wound healing, tumor growth, and metastasis." (PMID 37334378, 2023). "In this study, the nanobubbles served as a carrier to deliver a mixture of Cathepsin K (CTSK) siRNA and cerium oxide nanoparticles (CeNPs) to inhibit CTSK secretion by osteoclast cells, which triggers osteoporosis and enhances mineralization with antioxidant properties of CeNPs." (PMID 37896153, 2023). "Moreover, expressions of genes involved in osteoclast differentiation, TNF, ACP5, and CTSK, were all increased in the osteoporosis group compared to those in the normal control group." (PMID 37339951, 2023). "Our study revealed 72 targets between DHT and osteoporosis, including CTSK, MMP13, MAPK14, CASP3, etc., suggesting that these targets are principally related to the inflammatory response, apoptosis, and oxidative stress, which is consistent with the results of GO and KEGG analyses." (PMID 36210855, 2022). "Nevertheless, cathepsin K remains a viable target in osteoporosis." (PMID 36012257, 2022). "In this regard, CTSK is currently an important target for osteoporosis therapy." (PMID 35972313, 2022). "Cathepsin K is a promising target for the treatment of osteoporosis." (PMID 36012257, 2022). "Odanacatib plays a quite important role in osteoporosis therapy by inhibiting CTSK." (PMID 36386169, 2022). "Cathepsin K (CatK) is a target for the treatment of osteoporosis, arthritis, and bone metastasis." (PMID 35144520, 2022). "Cathepsin K, a lysosomalcysteine protease, seems to be the most important enzyme involvedin osteoclastic bone resorption, and its inhibitors were promisingfor the treatment of osteoporosis." (PMID 33723999, 2021). "Moreover, several cathepsin K inhibitors are currently in clinical trials as potential drugs for osteoporosis and osteoarthritis." (PMID 34465741, 2021). "RANK and CTSK are promising therapeutic targets for osteoporosis." (PMID 32405514, 2020). "In addition to osteoblasts, AAV9 targets OCs to drive RNAi-mediated silencing of the key OC regulators RANK and CTSK, which we show have clinical relevance as genetic targets to prevent osteoporosis." (PMID 32405514, 2020). "CTSK is a target protease for osteoporosis, which has attracted much attention in recent years." (PMID 33100272, 2020). "As a lysosomal cysteine protease, CTSK has been intensively investigated in the osteoporosis." (PMID 32620106, 2020). "Further, cathepsin K clinical inhibitors for treatment of osteoporosis might have potential to attenuate cancer." (PMID 32668602, 2020). "Many proteolytic enzymes such as MMP-2, MMP-9, or cathepsin-K were involved in bone remodeling process, and MMPs were key degrading enzyme expressed in either physiological or pathological conditions including osteoarthritis, and osteoporosis." (PMID 32165922, 2020). "In particular, therapeutic inhibition of cathepsins was the driving force in the field since the discovery that cathepsin K has a crucial role in bone resorption and thus in osteoporosis, and that cathepsin S is the key enzyme in the MHC II-mediated immune response." (PMID 30897858, 2019).
osteoporosis (continued). "However, the problem was already at least partially raised with Balicatib (Novartis), the first cathepsin K inhibitors that entered clinical trials for osteoporosis treatment and was discontinued after Phase II." (PMID 30897858, 2019). "Since newly developed agents for osteoporosis, such as antisclerostin antibody (Romosozumab) and the small molecule inhibitor of Cathepsin K (Odanacatib) show off-target cardiovascular and cerebrovascular events in clinical trials, a bone-specific treatment strategy must be developed." (PMID 31273195, 2019). "A number of compounds that inhibit cathepsin k have also been used to treat osteoporosis." (PMID 31281368, 2019). "Cathepsin K releases type I collagen crosslinks such as N-telopeptides of type I collagen (NTX) and C-telopeptides of type I collagen (CTX), which are widely used as diagnostic biomarkers for evaluation of osteoporosis." (PMID 28629344, 2017). "Furthermore, a cathepsin K inhibitors reduced the urinary CTX-II level in patients with osteoporosis and showed a cartilage protective effect in several models of RA and osteoarthritis." (PMID 26949397, 2016). "Therefore, many cathepsin K inhibitors have been developed and are likely to be the next generation of therapy for bone resorption diseases such as osteoporosis." (PMID 26949397, 2016). "In this article, we review three rare skeletal disorders with case descriptions, pycnodysostosis and the craniotubular hyperostoses sclerosteosis and van Buchem disease that led to the development of cathepsin K and sclerostin inhibitors, respectively, for the treatment of osteoporosis." (PMID 26892377, 2016). "Cathepsin K, a cysteine protease active at acidic pH, is the most abundant collagenase in osteoclasts, and its excessive expression in the bone and cartilage has been found to result in osteoporosis and arthritis, respectively." (PMID 25374443, 2014). "Hence, more detailed investigations concerning other potential roles of this protease are essential, especially considering the entry of cathepsin K inhibitors into clinical treatment of osteoporosis." (PMID 21794126, 2011). "Inhibitors of cathepsin K are in clinical trials for treatment of osteoporosis." (PMID 21794126, 2011). "Cathepsin K inhibitors, which block the activity of cathepsin on bone resorption lacunae, may be a new therapeutic option in osteoporosis." (PMID 20948576, 2010). "Our results indicate that both Rab32 and Rab38 may serve as drug targets for suppressing osteoclast function and may be developed like a bisphosphonate or like odanacatib, a CTSK inhibitor, as a therapeutic agent for rheumatoid arthritis, osteoporosis, and periodontitis." (PMID 37793839, 2023). "Importantly, FCL showed strong binding activities to the cathepsin K and mitogen-activated proteinkinase kinase 1 (MEK1), which indicated that FCL may possess anti-osteoporosis potentials targeting cathepsin K and MEK1." (PMID 34203392, 2021). "Therefore, several cathepsin K inhibitors have been examined as potential therapy for osteoporosis." (PMID 28629344, 2017). "Types of interaction with the Cathepsin K protein (PDB ID:1atk), one of the protease responsible for osteoporosis‐induced bone resorption, with the docking score energies of the dominant molecules in Gypsophila eriocalyx." (PMID 39188072, 2025). "ONO-5334, another CTSK inhibitor, was evaluated for its effects in ovariectomized (OVX) cynomolgus monkeys, which exhibit an osteoporosis-like phenotype." (PMID 39392536, 2024). "In osteoporosis treatment, for instance, the bisphosphonate alendronate could be used as a bone resorption inhibitor and a bone-targeting molecule; if conjugated with Cathepsin K-targeting siRNA to disrupt resorption, it may increase the overall effectivity of osteoporosis treatment." (PMID 37504868, 2023). "The inhibitors of cathepsin K (CatK) significantly affect bone turnover, bone mineral density (BMD) and bone strength in the patients with osteoporosis." (PMID 28304382, 2017).
osteoporosis (continued). "ONO-5334 is an orally available cathepsin K inhibitor with established efficacy for increasing BMD and proven safety in a 2-year phase II study in osteoporosis (the OCEAN study)." (PMID 28629344, 2017). "Selective and reversible inhibitors of human Cathepsin K (CatK), including odanacatib (ODN), have been developed as potential therapeutics for the treatment of osteoporosis." (PMID 24321244, 2013). "These disappointing results have led to a collapse of research strategies based on cathepsin K inhibitors—but while osteoporosis implication requires systemic application of ODN, our concept is based on the topical application of this cathepsin K inhibitor—the coating of implants." (PMID 40908780, 2025). "Similarly, B1W significantly downregulated the mRNA expression of the osteoporosis-related genes c-Fos, TRAP, CTSK, DC-STAMP and OSCAR." (PMID 39982961, 2025). "CTSK is a target of drugs such as relacatib, which is an anti-osteoporosis drug that is not Food and Drug Administration-approved." (PMID 37893075, 2023). "In our study, we used CTSK-Cre mice to study the changes of 11β-HSD1 in the mouse bone marrow cavity, which more precisely confirmed the role of 11b-HSD1 in osteoclasts under OVX condition, and better explained the role of 11β-HSD1 in osteoporosis." (PMID 37496992, 2023). "Moreover, we labeled BMMs or OCs with CD11b or CTSK and found Bhlhe40 upregulation in BMMs and OCs from ovariectomized (OVX)-induced osteoporosis mice compared to those from sham-operated control mice." (PMID 35619122, 2022). "CTSK inhibitors have been proved successful improving osteoporosis; however, concerns emerged over off-target effects of the inhibitors against other CTSs and CTSK inhibition at nonbone sites (i.e., skin, and cardiovascular and cerebrovascular sites)." (PMID 32326609, 2020). "Unfortunately cathepsin K inhibitors did not lead to new osteoporosis medication because of serious side effects (stroke)." (PMID 32733380, 2020). "Furthermore, these Ca extracts increased the expression levels of BMP-2, Wnt3a, SMAD5, RUNX2, osteocalcin and COL-1 in an in vivo model of osteoporosis, while they decreased TRAP, cathepsin K and RANK expression levels." (PMID 28513557, 2017). "Currently progression in development of newer agents such as cathepsin k inhibitor, strontium ranelate, AMG785, and AMG167 not only have increased the available options for treating osteoporosis, but also have opened doors of opportunity to improvements in the effective treatment." (PMID 28173850, 2017). "Furthermore, another cathepsin K inhibitor, ONO-5334, decreases urinary CTX-II/Cr with a similar inhibition rate to urinary NTX/Cr in patients with osteoporosis/osteopenia." (PMID 26949397, 2016). "We confirm these findings here and demonstrate that odanacatib (ODN), Merck’s cathepsin K inhibitor and post-clinical Phase III drug candidate for treatment of osteoporosis, decreases worm burden by 73% at the same dose with a 51% reduction in the parasite’s CP activity." (PMID 27384569, 2016). "Furthermore, CTSK, CSF1, TNFSF11, CTNNB1, TNFRSF11A, and TNF may be the most promising osteoporosis markers." (PMID 37893075, 2023). "Due to the high prevalence of osteoporosis in the postmenopausal Chinese women visiting our outpatient clinics, we failed to obtain the results of the differences of serum cathepsin K levels between subjects with postmenopausal osteoporosis and healthy postmenopausal controls." (PMID 32117071, 2020). "Importantly, none of these prior studies examined the effect of cathepsin K inhibition following a period of bone mass depletion, reflecting the clinical state of osteoporosis." (PMID 30406161, 2018). "The fact that cathepsin K could be involved in many prominent musculoskeletal diseases such as OA, RA and osteoporosis insinuates that it may not be a distinct etiological component in OA pathophysiology." (PMID 25889265, 2015).